SLAMF9 (SLAM family member 9)
Description:
May play a role in the immune response.
Synonyms: CD2F-10; CD84-H1; CD2F10; SF2001; CD84H1
Tractability: Antibody: UniProt predicts a signal peptide or a membrane-spanning region.
Gene: Protein-coding gene on chromosome 1 (159,951,492 to 159,954,237, reverse strand). Ensembl gene ENSG00000162723.
Subcellular location: Membrane
Gene Ontology:
Biological process: immune response; T cell activation
Cellular component: cell surface; external side of plasma membrane; membrane
Genetic constraint (gnomAD): Loss-of-function variants: 21 observed, 28.18 expected, observed/expected ratio (o/e) 0.75, 90% interval 0.53 to 1.07. The upper end of that interval is the gene's LOEUF score, 1.07, which puts it in group 4 of 6, group 1 being the genes least tolerant of losing a copy. Missense variants: 340 observed, 359.98 expected, observed/expected ratio (o/e) 0.94, 90% interval 0.86 to 1.03. Synonymous variants: 126 observed, 133.6 expected, observed/expected ratio (o/e) 0.94, 90% interval 0.81 to 1.09.
Homologues: Orthologues: chimpanzee SLAMF9 (97% identical), macaque SLAMF9 (85% identical), rabbit SLAMF9 (67% identical), guinea pig SLAMF9 (65% identical), dog SLAMF9 (61% identical), rat Slamf9 (58% identical), mouse Slamf9 (57% identical), pig SLAMF9 (55% identical), zebrafish si:cabz01074946.1 (13% identical). Paralogues in human: CD84 (29% identical), SLAMF6 (28% identical), LY9 (28% identical), SLAMF7 (25% identical), SLAMF8 (21% identical), CD244 (19% identical), SLAMF1 (18% identical), CD2 (14% identical), CD48 (14% identical).
Diseases named in the same sentence as SLAMF9 in open-access papers:
SLAMF9 is named in the same sentence as 19 diseases in open-access papers, as found by Europe PMC text mining. Sharing a sentence is not in itself a finding about the gene and the disease. The quoted sentences say what the papers report.
melanoma (3 papers, 2018 to 2024). A malignant, usually aggressive tumor composed of atypical, neoplastic melanocytes. "The presence of SLAMF9+ tumor-associated macrophages (TAMs) in 73.3% of human melanomas." (PMID 37835502, 2023). "SLAMF9 expression in melanocytic lesions may therefore indicate a genetic predisposition to develop a malignant melanoma." (PMID 30232321, 2018). "In vitro experiments showed that SLAMF9 gene expression was upregulated in murine bone marrow-derived macrophages stimulated with tumor-conditioned media of B16F10 melanoma cells." (PMID 38476238, 2024). "SLAM8 seems vital in modulating inflammatory responses, whereas recent studies indicate SLAMF9’s expression in specific cancerous cell lines, suggesting a potential role in melanoma cytokine production and macrophage dynamics." (PMID 37835502, 2023). "SLAMF9, a recent debutant to the immunoglobulin superfamily of receptors, is expressed on TAMs across both mouse and human melanomas." (PMID 37835502, 2023). "SLAMF9 expression was observed in melanocytic cells of 20% of melanomas and a mere 2.3% of nevi from melanoma patients." (PMID 37835502, 2023). "This review delves into the roles of specific SLAM members, such as SLAMF8 and SLAMF9, and their impact on tumor progression in cancers like colorectal cancer and melanoma." (PMID 37835502, 2023). "In this study, Slamf9 was discovered by gene expression analysis of BMDM stimulated with TCM from B16F1 melanoma cells." (PMID 30232321, 2018). "SLAMF9+ macrophages were identified in human and murine melanomas by using self-generated antibodies against human and murine SLAMF9." (PMID 30232321, 2018). "First, one exemplary slide of each pathological melanoma stage (stages I–IV) was immunohistochemically stained, revealing the presence of SLAMF9+ inflammatory cells in all four stages." (PMID 30232321, 2018). "In situ hybridization confirmed the existence of inflammatory cells positive for Slamf9 mRNA in human melanomas and further identified some Slamf9-mRNA+ melanoma cells." (PMID 30232321, 2018). "This antibody was used to detect Slamf9+ macrophages in subcutaneously grown murine B16F1 melanomas." (PMID 30232321, 2018). "Twenty percent of the examined melanomas and 2.3% of the naevi of melanoma patients also showed SLAMF9 expression by melanocytic cells." (PMID 30232321, 2018). "A comprehensive immunohistochemical analysis of tissue microarrays detected SLAMF9+ TAM in 73.3% of human melanomas, but also in 95.5% of naevi of melanoma patients and in 50% of naevi from healthy controls." (PMID 30232321, 2018). "As already seen by in situ hybridization, SLAMF9 expression in melanoma and naevi of melanoma patients was not limited to macrophages." (PMID 30232321, 2018). "Finally, SLAMF9-expressing TAMs have been detected in 73.3% of human melanomas, 95.5% of naevi of melanoma patients, and 50% of naevi of healthy controls." (PMID 38476238, 2024). "Fully grasping the role of SLAMF9+ TAMs in melanoma’s development and progression could spotlight this molecule as a crucial therapeutic target in the near future." (PMID 37835502, 2023). "As delineated in the preceding sections, members of the SLAM family, notably SLAMF8 and SLAMF9, play a dynamic role in tumor-immune modulation, profoundly affecting the progression and therapeutic outcomes of malignancies like colorectal cancer and melanoma." (PMID 37835502, 2023). "A comprehensive immunohistochemical analysis of two tissue microarrays (TMA) composed of 107 melanocytic lesions (45 malignant melanomas, 44 naevi of melanoma patients and 18 naevi of healthy controls) detected SLAMF9+ cells in 79.5% of all analyzed tissue samples." (PMID 30232321, 2018). "In addition, the exact functional impact of SLAMF9+ TAM for melanoma development and progression needs to be evaluated in more detail to identify its potential as a future therapeutic target." (PMID 30232321, 2018). "The melanoma-derived supernatant significantly induced gene expression of human Slamf9." (PMID 30232321, 2018).
melanoma (continued). "In addition, 20% of melanomas and 2.3% of naevi from melanoma patients displayed a positive SLAMF9 expression also in melanocytic cells." (PMID 30232321, 2018). "SLAMF9 plays an important role in melanoma biology, which is highlighted by the fact that we found SLAMF9+ TAM not only in subcutaneously implanted murine B16F1 melanoma but also in 73.3% of human melanomas stained with our self-generated peptide anti-SLAMF9 antibody." (PMID 30232321, 2018). "Further studies are required to evaluate whether SLAMF9 classifies as a promising future therapeutic target in melanoma." (PMID 30232321, 2018). "SLAMF9+ TAM were spotted in 73.3% of melanomas and in 95.5% of naevi from melanoma patients, while only 50% of naevi from healthy donors were infiltrated by SLAMF9+ macrophages." (PMID 30232321, 2018). "The induction of human and murine SLAMF9 requires pro-inflammatory stimulators such as IFN-γ and LPS or TCM from melanoma cells." (PMID 30232321, 2018). "SLAMF9 was also expressed in melanocytes in 20% of melanoma samples and 2.3% of naevi from melanoma patients but not in healthy controls." (PMID 38476238, 2024). "Strikingly, in 20% the melanoma cells themselves were SLAMF9 positive while only 2.3% of melanocytic naevus cells derived from melanoma patients and none of the naevi from healthy donors showed SLAMF9 expression." (PMID 30232321, 2018). "SLAMF9 has not been assessed in great detail in the solid cancer setting, but research showing expression on TAMs in melanoma suggests it might be a target for further research." (PMID 38476238, 2024). "Expression of Slamf9, a member of the signaling lymphocytic-activating molecule (Slam) immunoreceptor family, was found to be upregulated in a gene expression analysis of murine bone marrow-derived macrophages (BMDM) stimulated with tumor-conditioned medium of B16F1 melanoma cells." (PMID 30232321, 2018).
colorectal cancer (2 papers, 2023 to 2025). A primary or metastatic malignant neoplasm that affects the colon or rectum. "SLAMF9 has been associated with poor prognosis in colorectal cancer, where its elevated expression correlates with reduced patient survival and increased tumor aggressiveness." (PMID 41162970, 2025).
liver inflammation (2 papers, 2022 to 2025). "Limited studies have indicated that combined deficiency of SLAMF8 and SLAMF9 prevents endotoxin-induced liver inflammation by downregulating TLR4 expression on macrophages, and SLAMF8 can negatively regulate ROS production by macrophages." (PMID 35432371, 2022). "The combined activation of SLAMF9 and SLAMF8 induces macrophage activity, while their downregulation modulates the expression of TLR4, thereby attenuating endotoxin-induced liver inflammation." (PMID 40473938, 2025).
viral infection (2 papers, 2019 to 2024). "The ability of SLAMF9 to control pDCs function suggests that this receptor may play a role indirectly in controlling viral infections, as pDCs are known to be critical in this respect." (PMID 31744090, 2019). "While blockade of SLAMF1 and SLAMF3 to directly prevent virus interactions are one approach, modulation of SLAMF9 signaling may allow for an indirect approach to treat acute or chronic viral infections." (PMID 31744090, 2019). "Our current study further extends the potential function of SLAMF9+ macrophages, and also the SLAM-family receptors in viral infection and pulmonary diseases." (PMID 39414783, 2024).
atherosclerosis (1 paper, 2024). A disease characterized by the build-up of fatty material and calcium deposition in the arterial wall resulting in partial or complete occlusion of the arterial lumen. "Slamf9, used to annotate a subtype of Trem2hi macrophages in murine atherosclerosis, was parallelly expressed in FoamMac_3 in human plaques." (PMID 39766313, 2024).
autoimmune disease (1 paper, 2022). A disorder resulting from loss of function or tissue destruction of an organ or multiple organs, arising from humoral or cellular immune responses of the individual to their own tissue constituents. "A review of signaling lymphocytic activation molecule (SLAM) family proteins by Dragovich and Mor (2018) suggested that SLAMF9 was a potential therapeutic target for inflammatory and autoimmune diseases." (PMID 34931260, 2022).
Burkitt lymphoma (1 paper, 2024). A rare form of malignant mature B-cell non-Hodgkin lymphoma. "RT-PCR analysis showed the expression of SLAMF9/CD84-H1 in dendritic cells, monocytes, the THP-1 monocytic cell line, Jurkat, and HuT78 T-lymphoid cell lines as well as Raji and Ramos Burkitt lymphoma cell lines." (PMID 38612827, 2024).
chondrosarcoma (1 paper, 2022). A malignant cartilaginous matrix-producing mesenchymal neoplasm arising from the bone and soft tissue. "We detected the expression of SLAMF9 protein in 20 chondrosarcoma tissues by immunohistochemical staining." (PMID 34931260, 2022). "We found that SLAMF9 was positive in all chondrosarcomas evaluated, and showed a specific distribution in chondrosarcoma chondrocytes, but minimal expression in normal cartilage tissue adjacent to cancer." (PMID 34931260, 2022). "The chondrocyte cluster with specific expression of the immune gene SLAMF9 attracted our attention, and we found that the protein was specifically expressed in chondrosarcoma tissues by immunohistochemical staining." (PMID 34931260, 2022). "Immunohistochemistry revealed the SLAMF9 gene was specifically expressed in non-immune cells of chondrosarcoma, but was barely expressed in the normal cartilage tissues adjacent to chondrosarcomas." (PMID 34931260, 2022). "We speculate that SLAMF9 is a specific marker in non-immune cells of chondrosarcoma and shows great potential for interfering with tumor function." (PMID 34931260, 2022).
Salmonella Infections (1 paper, 2020). Infections with bacteria of the genus SALMONELLA. "Deficiencies in SLAMF9 expression lead to altered pro‐inflammatory cytokine production in human cells and reduced capacity to clear Salmonella infection in mice." (PMID 31880316, 2020). "In this study, we have shown that SLAMF9‐deficient mice have impaired clearance of systemic Salmonella infection, and suppression of SLAMF9 expression in human THP‐1 cells dramatically reduces their ability to produce pro‐inflammatory cytokines TNF‐α, IL‐1β and GM‐CSF." (PMID 31880316, 2020). "In summary, we have identified SLAMF9 as an important mediator of inflammation and a contributor to antibacterial immune responses to systemic Salmonella infection." (PMID 31880316, 2020).
tumor (7 papers, 2018 to 2025). "SLAMF9 affects pro-inflammatory cytokine production and migration in murine and human melanoma tumor-associated macrophages." (PMID 37251372, 2023). "SLAMF9 (also known as CD2F10) is found on myeloid cells, plasmacytoid DCs, tumor-associated macrophages, peritoneal B1 cells, and peritoneal macrophages." (PMID 37251372, 2023). "In previous studies, SLAMF9 was reported to mediate immune response by regulating homeostasis of plasmacytoid dendritic cells (pDC), regulating common macrophages and tumor-associated macrophages." (PMID 34931260, 2022). "Immunohistochemical staining revealed an accumulation of Slamf9+ macrophages predominantly in the periphery of this tumor." (PMID 30232321, 2018). "SLAMF9 is specifically and highly expressed in the chondrocyte subsets of tumor samples." (PMID 34931260, 2022). "Therefore, targeting SLAMF9 may be beneficial to enhance anti-tumor immunity." (PMID 30232321, 2018). "Further study on the role of SLAMF9 and GRK3 in the microenvironment and tumor progression of laryngeal chondrosarcoma may provide clues for laryngeal chondrosarcoma pathogenesis and potential new therapeutic targets." (PMID 34931260, 2022). "Since both SLAMF8 and SLAMF9 lack intracellular signaling motifs, SLAMF9 may also reduce migration by preventing the assembly of the Nox2 complex potentially both in TAM and tumor cells." (PMID 30232321, 2018).
infection (6 papers, 2016 to 2024). The state of being infected such as from the introduction of a foreign agent such as serum, vaccine, antigenic substance or organism. "In particular, IFN-λ inoculation markedly elevated Fabp4 and Slamf9 transcriptions in the lungs of CoV2+ hamsters from an early stage of infection." (PMID 36524125, 2022). "Upon systemic challenge with Salmonella enterica Typhimurium, Slamf9−/− mice were impaired in their ability to clear the infection from the liver." (PMID 31880316, 2020). "We identified that a group of Slamf9+ macrophages in the lung, which were specifically induced from monocytes during the acute infection phase and kept active proliferation, could recruit neutrophils to collaboratively clear SARS-CoV-2 from hamster lungs." (PMID 39414783, 2024). "Moreover, Isg12+Cst7+ neutrophils expressed Cd274 and Il10rb, potentially interacted with activated cytotoxic T cells and Slamf9+ macrophages, and jointly established the favoring niches for the resolution of inflammation at the late stage of infection." (PMID 39414783, 2024). "To evaluate whether SLAMF8 can modulate the expression of TLR4 and SLAMF9 and, therefore, influence the observed phenotype in SLAMF8-deficient mice, we analyzed their expression in pMø by RT-PCR after treatment with IFNγ (100 U/ml for 16 h) and infection with S. typhimurium at different time points." (PMID 35837407, 2022). "Noticing the disappearance of Slamf9+ and Cd38+ macrophages after SARS-CoV-2 clearance at d14, we speculated that the specific transcriptional state of Slamf9+ macrophages may be induced by engulfment or infection of SARS-CoV-2, which needs to be further investigated." (PMID 39414783, 2024).
bacterial infection (1 paper, 2020). "Taken together, these data implicate SLAMF9 in the initiation of inflammation and clearance of bacterial infection." (PMID 31880316, 2020).
SLAMF9 also shares sentences with these, for which no sentence is quoted: cancer (2 papers); breast carcinoma (1); COVID-19 (1); experimental autoimmune encephalomyelitis (1); osteoarthritis (1); pulmonary diseases (1); Sepsis (1).